LATS1 (large tumor suppressor kinase 1)
Diseases named in the same sentence as LATS1 in open-access papers (continued):
Sharing a sentence is not in itself a finding about the gene and the disease.
tumor (continued). "Previous studies have also demonstrated the oncogenic roles of MST1/242 and LATS1/243 in human tumours, including proliferation, apoptosis, and glucose metabolism." (PMID 37665055, 2023). "To investigate the role of Lats1 in regulating tumor growth and its potential connection with macrophage-derived exosomes under hypoxic conditions, we performed MS analysis to identify proteins present in these exosomes." (PMID 38022589, 2023). "The ectopic expression of LATS1 decreased proliferation and invasion of GC cells in vitro and impaired tumor growth and metastatization in vivo through YAP inhibition, whereas LATS1 depletion rescued the invasive phenotype." (PMID 36635265, 2023). "The neurofibromatosis type 2 (NF2) gene product, Merlin, is an important tumor suppressor that acts upstream of LATS1 to negatively regulate YAP in the Hippo pathway." (PMID 37834234, 2023). "As the core effector molecule of the Hippo signaling pathway, LATS1 is key to tumor therapy research, and the regulatory element targeting LATS1 has also become a hot topic in tumor research." (PMID 36609396, 2023). "Based on this finding, a SuperHippo peptide covering the WWC1/2/3-LATS1/2 interaction interface was thus developed to robustly activate LATS1/2 kinase activity, demonstrating excellent tumor suppression effects in multiple tumor models." (PMID 36924251, 2023). "TCGA analysis revealed that large tumor suppressor kinase 1 (LATS1), a key tumor suppressor of the Hippo pathway, was significantly downregulated in tumors; the expression of LATS1 was increased by tazemetostat." (PMID 36808829, 2023). "NEX-Cre–mediated deletion of the other two members of the NDR kinase family, LATS1 and LATS2, causes YAP1 activation and tumour formation in brain." (PMID 36446521, 2023). "Overexpression of circXRN2 significantly reduced lung metastatic nodules compared with the normal control group, while the tumor nodules were significantly increased in cells treated with circXRN2 overexpression along with knockdown of LATS1." (PMID 37684641, 2023). "In this study, we provide the first comprehensive evaluation of four Hippo pathway components’ (YAP, TAZ, TEAD4 and LATS1) expression pattern in a cohort of TETs, with interesting results regarding their levels and distribution within tumor cells." (PMID 37509515, 2023). "In about 30–40% of malignant pleural mesothelioma cases, for example, the NF2 (Neurofibromatosis type 2) tumor suppressor gene is somatically inactivated, leading to defective recruitment of LATS1/2 kinases to the plasma membrane and impaired Hippo signaling." (PMID 38139762, 2023). "YAP1 activity, particularly its phosphorylation level, is commonly regulated by the LATS1/2 kinase of the Hippo pathway and is critical for tumor initiation, progression, and metastasis." (PMID 36735162, 2023). "NKX2–2AS modulates SHH-induced MB formation in vitro by functioning as miRNA sponge for miR-103 and miR-107, thereby de-repressing their tumor suppressive targets BTG2 and LATS1 and limiting tumor cell proliferation and migration." (PMID 36923440, 2023). "Considering the important role of LATS1 in tumor suppression, we investigated the exact mechanism of METTL3-mediated m6A modification of LATS1." (PMID 36609396, 2023). "We previously found that HERC4 is an E3 ligase for the tumor suppressor LATS1 and destabilizes LATS1 by promoting its ubiquitination of LATS1." (PMID 36609396, 2023). "Conversely, the core kinase cassette of the Hippo pathway, which comprises MST1/2 and LATS1/2, has demonstrated tumor suppressive effects in several cancer types." (PMID 37251938, 2023). "Accumulating studies have shown that LATS1 serves as a tumor suppressor; however, the mechanism by which LATS1 stability is regulated remains elusive." (PMID 36803368, 2023). "MOB1B is identified as a tumor suppressor, and it interacts with and activates LATS1/2 kinase, which is critical for fully activating LATS1." (PMID 37076815, 2023).
tumor (continued). "MST1/2 and LATS1/2 (upstream core kinases components) are important tumour-suppressors of the Hippo pathway." (PMID 36552980, 2022). "Evaluation of the tumor suppressors, LATS1/2, the direct upstream regulators of Hippo/YAP and TAZ, showed that LATS1 was significantly reduced, whereas LATS2 was not affected." (PMID 35995996, 2022). "While this increase in apoptosis does not require the expression of RASSF1A in BRAFV600E mutant cells, re-expression of this tumour suppressor increases the level of apoptosis induced by LATS1." (PMID 35941108, 2022). "QRT-PCR was utilized to detect circ_0067741, microRNA-183-5p (miR-183-5p) and large tumor suppressor 1 (LATS1) expressions in tumor tissues of 30 LUAD patients and LUAD cell lines (A549, Calu-3, H1299 and H1975)." (PMID 35435136, 2022). "Another study showed LATS1 low expression in GC patients, and this was correlated with lymph node metastasis, poor prognosis, and tumour relapse." (PMID 35565411, 2022). "Neurofibromin-2 (NF2) promotes tumor suppression in the LATS1/2 canonical hippo pathway through MST1." (PMID 35804016, 2022). "Studies have found that the Hippo pathway kinase LATS1/2 in tumor cells can affect tumor growth, and MINK1 is involved in the expression of Hippo pathway kinase." (PMID 36303542, 2022). "Supporting this is our finding that targeted deletion of LATS1/2 in Sox9-expressing cells using a Sox9CreERT2 model resulted in basal-like tumor development like that observed using a K8CreERT2 model." (PMID 36443313, 2022). "We leveraged this unique characteristic of mouse melanomagenesis to test if Lats1/2−/− tumor formation was also promoted by depilation, suggesting a melanocytic origin." (PMID 35768444, 2022). "In sum, our research suggests the existence of a regulatory mechanism that can be summed up as follows: “Ionizing Radiation → LncRNA CRYBG3 → ADF/CFL1 --- |F-actin --- | LATS1/2 --- | YAP/TAZ → tumor proliferation, migration and invasion”." (PMID 35246511, 2022). "LATS1 is a tumour suppressor which, together with MST1/2 and YAP, forms the core signalling unit (MST1/2-LATS1/2-YAP) of the MST2/Hippo pathway (herein MST2 pathway)." (PMID 35941108, 2022). "For example, SRC-mediated LATS1 phosphorylation abolished the tumor suppressor activity of LATS1 and induced tumorigenesis in a YAP-dependent manner in BC cells." (PMID 36581908, 2022). "LATS1 functions as a tumor suppressor to diminish CRC growth and migration via glioma-associated oncogene homolog 1 (Gli1) downregulation." (PMID 36289774, 2022). "Overall, the current work shows that SMAC-dependent apoptosis is regulated by the LATS1 tumour suppressor and supports the idea that LATS1 is a signalling hub that regulates the crosstalk between the MST2 pathway, the apoptotic network and the ERK pathway." (PMID 35941108, 2022). "LATS1/2, the Hippo pathway core kinase, is a tumor suppressor that reduces the oncogenic nuclear role of YAP/TAZ and TEA domain transcription factor (TEAD)." (PMID 34565286, 2021). "Our current model summarizes these data, which suggest that BMI1 promotes tumor cell growth by inhibiting LATS1/2 phosphorylation and allowing YAP/TAZ/TEAD to transcribe canonical target genes (such as AXL, CYR61, and CTGF)." (PMID 33523558, 2021). "In the Hippo signaling pathway, STK3/4 and LATS1/2 play antiproliferative roles and should act as tumor suppressors." (PMID 34150758, 2021). "Accordingly, the purpose of the study was to assess the role of LATS1 in melanogenesis and oxidative stress and its influence on tumor growth." (PMID 33803640, 2021). "The overexpression of miR-92a-3p downregulated LATS1, which was a potential tumor suppressor in CC stem cells." (PMID 34869346, 2021).
tumor (continued). "Nkx2-2as functions as a ceRNA to sequester miR-103/107 and miR-548 m, and it downregulated the tumor suppressors BTG2/Tis21/PC3 and LATS1/2, promoting tumor growth both in vitro and in vivo." (PMID 34552822, 2021). "Our analysis revealed tumor-infiltrating CD8+ T-cells, particularly CD8+ effector memory T-cells, were mainly enriched in MPM harboring LATS1/2 mutation, compared with NF2-mutant MPM and other cancer types." (PMID 33805359, 2021). "Although more in-depth studies are needed to clarify the mechanisms regarding the Gli1 regulation by LATS1 in CRC, our results strongly confirmed that the LATS1 is a tumor suppressor in CRC." (PMID 35003351, 2021). "For example, showed that although inactivation of LATS1 and LATS2 led to enhanced anchorage-independent cell growth in vitro, it also caused increased tumor immunogenicity and tumor regression in vivo." (PMID 34150758, 2021). "For example, inactivation of the serine/threonine kinase LATS1, which directly phosphorylates/inactivates YAP and TAZ, caused CIN and tumor formation." (PMID 34615513, 2021). "The simultaneous quadruple deletion of YAP, TAZ, and LATS1/2 in the peritumoral tissue increased cancer cell proliferation and tumor burden." (PMID 33430180, 2021). "LATS1, as the major kinase component of the Hippo pathway, exerts a significant role to control tumor cell proliferation, growth, and migration 10-13." (PMID 35003351, 2021). "It is worth mentioning that LATs1 is a tumor suppressor that can promote the activation of Hippo signaling." (PMID 34394353, 2021). "We first investigated the mRNA expression of LATS1 via the GEPIA database, and the results showed decreased mRNA level of LATS1 in CRC tumor tissues (T) compared to the normal controls." (PMID 35003351, 2021). "We demonstrated that LATS1 is highly involved in melanin biosynthesis as well as in tumor growth control." (PMID 33803640, 2021). "In vitro experiments showed that overexpression of LATS1 inhibits the expression of YAP (the CYFRA21-1 susceptibility gene), thereby inducing G1 phase arrest, inhibiting cell proliferation and promoting tumor cell apoptosis." (PMID 34630106, 2021). "Investigation for the expression of LATS1 protein in 102 CRC tumor tissues and 57 normal tissues was performed using immunohistochemistry (IHC) analysis." (PMID 35003351, 2021). "A different compound is Decursin, extracted from the roots of Angelica gigas, which has been demonstrated to augment destruction of YAP by increasing the level of phosphorylated LATS1 and β-TrCP in tumor cells." (PMID 33924049, 2021). "In contrast, tumor growth of U87MG-PMEPA1a cells was decreased with overexpression of the tumor suppressor LATS1 or knockdown of YAP." (PMID 31605013, 2020). "Next, we wanted to know if genes and proteins upregulated in nlsYAP5SA mice were also upregulated in LATS1/2 knockout mouse tumours." (PMID 32404936, 2020). "The Hippo signaling pathway is a tumor inhibition pathway that was discovered in recent years, of which LATS1 and LATS2 kinase are two important components and have many important biological functions." (PMID 32423384, 2020). "Supporting our finding, LATS1/2 can suppress cancer immunity, and their deletion improves tumor immunogenicity by enhancing anti-tumor immune responses." (PMID 32824422, 2020). "Mechanistically, LATS1/2-null tumor cells secrete nucleic acid-rich extracellular vesicles, which induce a type I interferon response via the Toll-like receptor-MYD88/TRIF pathway." (PMID 32983971, 2020). "Supporting the notion, PD-L1 (encoded by CD274) is the most significantly upregulated protein in LATS2-mutant MPM, and LATS1/2 deletion has recently been shown to enhance anti-tumor immune responses." (PMID 32824422, 2020). "Their involvement in tumor development is often associated with the inhibition of YAP/TAZ inhibitory kinases, notably PI3K (phosphoinositide 3-kinase), which inhibits LATS1/2." (PMID 32164350, 2020).
tumor (continued). "We focused on the relationship between LATS1/2 and these tumor immunity-related biological markers in a tumor immune microenvironment by analyzing 490 immunohistochemically stained samples from advanced GC patients." (PMID 32983971, 2020). "The blockade of LATS1 expression resulted in increased Srf-induced apoptosis and decreased cell viability in vitro, as well as reduced tumor growth in vivo." (PMID 33082313, 2020). "The YAP1 protein expression level is canonically regulated by the LATS1/2 kinase of the Hippo pathway and is critical for tumor initiation, progression, and metastasis." (PMID 33489890, 2020). "CRL4-DCAF1 ubiquitinates Large tumor suppressor kinase 1/2 (LATS1/2), and prevents Yes-associated protein (YAP) phosphorylation, thus inhibiting the Hippo tumour suppressor pathway and supporting tumour growth." (PMID 32629964, 2020). "Serial sections of paraffin embedded P20 LATS1/2 cKO mice brains showed periventricular multifocal tumours in continuity with the ependymal layer." (PMID 32404936, 2020). "In a tumor immune microenvironment, LATS1/2 knockout in tumor cells weakened the CD8+T cell functions, leading to tumor immune escape." (PMID 32983971, 2020). "To further test the ependymal origin of LATS1/2 cKO tumours, we performed ultrastructural examination using transmission electron microscopy (TEM)." (PMID 32404936, 2020). "Using genetic rescues by deleting YAP1 and TAZ from the same cells with LATS1/2 deletion, we demonstrated that either of these paralogs can lead to tumour formation." (PMID 32404936, 2020). "LATS1 is a tumor suppressor in the Hippo signaling pathway and inactivates the oncogenic transcriptional regulator YAP through phosphorylation at ser-127." (PMID 31605013, 2020). "Typically, although LATS1 plays a tumor suppressor role in the Hippo pathway, it also exerts a pro-survival function in the HCC cells." (PMID 33082313, 2020). "LATS1/2 have emerged as key regulators of various oncogenic or tumor-suppressive effectors, as well as epithelial–mesenchymal transition (EMT) mediators during cancer metastasis." (PMID 32041942, 2020). "Using immunofluorescence, we found that YAP1 downstream effectors identified in mRNA analysis, ANKRD1, AMOTL2 and AXL were increased in LATS1/2 cKO tumours." (PMID 32404936, 2020). "In LATS1/2 deletion induced tumours, YAP1 was highly expressed in the cytoplasm of all cells and was enriched in the nucleus in a subset of cells in tumour, in a mosaic fashion." (PMID 32404936, 2020). "LATS1, in addition to acting in the Hippo signaling pathway as a tumor suppressor, has other function." (PMID 33247672, 2020). "The monolayer wound healing and transwell assays also confirmed that overexpression of Lats1 reversed the overexpression of CRABP2 results promoting tumor cells invasion and metastasis." (PMID 31419991, 2019). "In growth factor-mediated YAP signalling via the MAPK and PI3K nexus, large tumour suppressor kinase 1 (LATS1), a tumour suppressor that phosphorylates YAP/TAZ, is repressed through reduced phosphorylation, thus enhancing the nuclear localization of YAP." (PMID 31429823, 2019). "Deregulation of the mammalian Hippo signalling components has been implicated in the formation of tumours and cancers, with loss of MST1/2, LATS1/2, SAV or MOB1 resulting in the development of different tumour types in mouse models." (PMID 30139767, 2019). "POPX2 can function to oppose the tumour suppressor function of the Hippo pathway by dephosphorylating LATS1, leading to increased nuclear YAP/TAZ." (PMID 30863499, 2019). "In contrast to its tumor suppressive role in the Hippo signaling pathway, we report that LATS1 exerts a pro-survival function in HCC cells in response to Srf treatment, i.e., an oncogenic activity." (PMID 31848340, 2019). "This is consistent with removing a negative regulator of LATS1, which resulted in increased LATS1 activity and its tumour suppressor function." (PMID 30863499, 2019).
tumor (continued). "Growing evidence demonstrates the critical role of LATS1 in regulating cell proliferation and the tumor immune response." (PMID 30718452, 2019). "The components of Hippo pathway (Mst1/2, Lats1/2 etc.)have been reported to play tumor suppressive roles in cancers." (PMID 31703744, 2019). "HERC4 is a new E3 ligase for the tumor suppressor LATS1 and destabilizes LATS1 by promoting the ubiquitination of LATS1." (PMID 30710319, 2019). "For example, when Lats1 is ubiquitinated, the kinase activity of Lats1 is reduced and subsequently inhibited by Hippo signaling only promotes cell proliferation, but also inhibits cell apoptosis and attenuates tumor suppressor function." (PMID 31191455, 2019). "our results defined NR1B2 as a tumor suppressor in KIRC that restricted EMT by the LATS1/2-YAP pathway." (PMID 31391070, 2019). "Another study revealed that LATS1/2-deficient cancer cells induce a type I interferon response via the host TLR signaling, enhancing cross-presentation of tumor antigens to boost the anti-cancer immune response." (PMID 31052239, 2019). "Tamoxifen treatment retarded tumor growth in all genotypes; however, Lats1-CKO PyMT tumors were relatively less inhibited than WT-PyMT or Lats2-CKO PyMT tumors." (PMID 30456386, 2018). "A working model is that agrin antagonizes the tumor-suppressive functions of Merlin and LATS1/2 kinase by regulating the cell-matrix adhesions." (PMID 29415512, 2018). "Mechanistically, LATS1/2‐null tumour cells secrete nucleic acid‐rich extracellular vesicles, which induce a type I interferon response via the Toll‐like receptor MYD88/TRIF pathway, thus improving tumour immunogenicity." (PMID 28782275, 2018). "MST1/2 and LATS1, the most upstream proteins in the Hippo signalling pathway, act as tumour suppressors of human cancers." (PMID 28782275, 2018). "Recently, it has been published that either deletion of LATS1/2 or overexpression of YAP/TAZ increases tumor immunogenecity and thus enhance its destruction by the immune system in vivo." (PMID 30619734, 2018). "For instance, MST1/2 and LATS1/2, the upstream kinases of the Hippo pathway, function as tumour suppressors in multiple human cancers." (PMID 28782275, 2018). "Firstly, the expression levels of MST1 and LATS1 were examined in both non-tumor tissues and PTC tissues." (PMID 30237435, 2018). "Among the seven TSGs showing evidence of pPA, the truncated LATS1 isoform is particularly similar to MAGI3pPA since previous studies have suggested that truncation products of LATS1 act to functionally oppose its tumor suppressive function." (PMID 29362392, 2018). "But, LATS1/2 is proved to inhibit tumor immunity and provides a concept for targeting LATS1/2 in cancer immunotherapy." (PMID 28893265, 2017). "We further characterized a circLARP4 derived from LARP4 gene and demonstrated that circLARP4 was a tumor suppressive factor in GC by sponging miR-424 and regulating LATS1 expression." (PMID 28893265, 2017). "In detail, Lats1/2 deletion induces interferon I response improving tumor vaccine efficacy; this mechanism opens possibilities in targeting Lats1/2 for cancer immunotherapy and suggests an additional function exerted by the Hippo pathway." (PMID 28467351, 2017). "Our findings suggest that LATS1 is a potential candidate tumor suppressor and inhibits the growth and metastasis of GC cells via downregulation of the YAP signaling." (PMID 26921249, 2016). "To examine the expression of LATS1 in GC tissues, we detected the expression level of LATS1 in 89 cases of GC patients with paired adjacent non-tumor tissue (ANTT) by IHC." (PMID 26921249, 2016). "LATS1 inhibits cell proliferation and vascular invasion and induces cell apoptosis and cycle arrest, indicating LATS1 as a tumor suppressor in human cancer." (PMID 26921249, 2016).